TGFB2 (transforming growth factor beta 2)
Diseases named in the same sentence as TGFB2 in open-access papers (continued):
Sharing a sentence is not in itself a finding about the gene and the disease.
infection (29 papers, 2008 to 2025). The state of being infected such as from the introduction of a foreign agent such as serum, vaccine, antigenic substance or organism. "Key inflammatory cytokines and acute-phase mediators (CXCL10, SAA3, THBS4) are down-regulated immediately upon infection, alongside TGFB2, low-density lipoprotein receptors, structural constituents and adhesion factors." (PMID 39863683, 2025). "As indicated in a pilot study, miR-141 was significantly expressed upon infection with influenza virus H5N1 to downregulate transforming growth factor beta 2 (TFG-β2) in infected cells." (PMID 37596622, 2023). "Both TGFβ genes were significantly upregulated upon infection with Ct; TGFβ1 and TGFβ2 showed a 2- and 7-fold increase in mRNA, respectively." (PMID 28660176, 2017). "We found that Ct infection strongly induces mRNA expression of TGFβ, particularly TGFβ2, in HCjE cells, in line with the finding that lung epithelial cells show enhanced secretion of TGFβ after infection with Ct." (PMID 28660176, 2017). "As observed in sheep, TGFB2 could be used by H. contortus to promote infection." (PMID 31615414, 2019). "Thus, the TGFB2 gene, that is induced by infection and expressed at a higher level in Holstein infected cells, was present in our H/S-DE data set (elevated 3.5 log2 fold) but was not identified as infection associated." (PMID 35061738, 2022). "These cells instead displayed a gradual increase in the expression of α-SMA, TGFβ2 and SMAD-target genes, and they exhibited faster migration only after 90 days of Ad-Cre infection." (PMID 26946493, 2016).
adenocarcinoma (6 papers, 2007 to 2023). A common cancer characterized by the presence of malignant glandular cells. "Loss of each regulatory interaction results in adenocarcinomas suggesting that regulation serves to prevent a GDF6 or TGFB2 promitotic signal from impacting the colon or endometrium, respectively." (PMID 36214621, 2022). "TGFβ1 and TGFβ2 have been implicated in FOXP3 induction in peripheral Tregs and adenocarcinoma expansion." (PMID 36973425, 2023).
connective tissue disorder (6 papers, 2015 to 2025). A disease involving the connective tissue. "She subsequently underwent testing using the same commercial 92 gene panel for connective tissue disorders, which was also negative but did detect a likely benign variant NM_003238.6 (TGFB2):c.755-6T>C." (PMID 39737004, 2024).
cardiovascular diseases (5 papers, 2019 to 2026). "For example, although Tgfb2−/− mice show remarkable defects in heart and vessel development, the role of TGF-β2 in adulthood cardiovascular diseases is less investigated." (PMID 38067167, 2023). "TGFß signaling can contribute to the pathogenesis of cardiovascular diseases, and TGFB2 was among the top differentially expressed genes in our previous study of gene dysregulation in OUD postmortem brain." (PMID 36713930, 2022). "TGFβ2, a cytokine, is involved in vascular function, and mutations in TGF β2 are found to be implicated in cardiovascular diseases such as vascular complications and aortic disease." (PMID 30699965, 2019).
vasculopathies (4 papers, 2014 to 2022). "Furthermore, in silico analyses indicated interactions of miR-199a-5p with HIF1A, Ets-1, and TGFB2 genes, which are associated with vasculopathy and reduced NO." (PMID 35204817, 2022). "Similar to other conditions known as TGF-β vasculopathies (MFS, which is caused by FBN1 mutations and LDS, which is caused by TGFBR1, TGFBR2, SMAD3 and TGFB2 mutations), the SLC2A10 loss of function activates the TGF-β signaling pathway." (PMID 25373504, 2014).
heart disease (3 papers, 2014 to 2025). "Thus, understanding the molecular regulation of TGFβ2-dependent ECM remodeling by YAP1 is an important step in elucidating the underlying mechanisms involved in the etiology of heart disease." (PMID 38132651, 2023). "A previous study showed that TGFB2 may correlate with heart disease and pulmonary function in mice." (PMID 24650256, 2014). "Further investigation to elucidate the role of the TGFβ2 and Hippo pathways in vivo in cushion mesenchymal differentiation and maturation and ECM remodeling and reorganization processes will lead to a better understanding of heart development and heart disease." (PMID 38132651, 2023).
inflammation (3 papers, 2007 to 2020). Aberrant reaction of the microcirculation characterized by movement of fluid and leukocytes from the blood into extravascular tissues. "TGFβ2 is a crucial mediator of the ocular inflammation in dry eye disease." (PMID 33162816, 2020).
proliferative retinopathy (3 papers, 2012 to 2022). "The present study characterized the expression profiles of the inflammatory cytokines VEGFα and TGFβ2 in the ERMs and ILMs in retinal disorders such as RRD, DR, and iERM." (PMID 29850215, 2018).
immune diseases (2 papers, 2018 to 2023). "Furthermore, several key genes (e.g., Csf1r, Ifnb1, IL-20, IL-22, IL-24, Jhdm1d, Csf1r, Ifnb1, IL-20, IL-22, IL-24, and Tgfb2 that regulate sex differences in immune diseases) were discovered." (PMID 30246031, 2018).
inflammatory myopathies (2 papers, 2025). "TGFB1 and TGFB3 were expressed at levels similar to other inflammatory myopathies, while their receptors—particularly those for TGFB2 and TGFB3—were more strongly upregulated in ANCA-negative VM than in other IIM subtypes." (PMID 41441888, 2025).
skeletal diseases (1 paper, 2023). "For example, Transforming growth factor beta 2 (Tgfb2) and Tgfb3 are both linked to skeletal diseases." (PMID 37378024, 2023).
TGFB2 also shares sentences with these, for which no sentence is quoted: diabetic nephropathy (7 papers); anaplastic astrocytoma (6); retinal diseases (6); uveitis (6); adenomyosis (5); age-related macular degeneration (5); Allergy (5); cardiomyopathy (5); astrocytoma (4); brain cancer (4); depression (4); dry eye (4); liver disease (4); osteoporosis (4); Anxiety (3); Arthritis (3); Cirrhosis (3); diffuse midline glioma (3); dilated cardiomyopathy (3); ischemia (3); mitral valve prolapse (3); nasal polyps (3); nasopharyngeal carcinoma (3); necrotizing enterocolitis (3); ovarian tumor (3); primary angle-closure glaucoma (3); proliferative diabetic retinopathy (3); Stroke (3); vascular EDS (3); acute myeloid leukemia (2).
A further 180 diseases each share a sentence with TGFB2 in 2 papers or fewer.